TNF (tumor necrosis factor)
Diseases named in the same sentence as TNF in open-access papers (continued):
Sharing a sentence is not in itself a finding about the gene and the disease.
Insulin resistance (continued). "Peripheral adipose tissue also plays a critical role in promoting inflammation and insulin resistance via increased production of pro-inflammatory tumour necrosis factor alpha (TNFα) and interleukin- (IL-) 6 in the setting of obesity." (PMID 24830559, 2014). "SCO also blunted the TNFα-mediated increase in IL-6, which is another pro-inflammatory cytokine that has been shown to induce insulin resistance in adipocytes." (PMID 24915004, 2014). "Once over-activated by TNF-α and IL-6, Th22 cells exacerbate insulin resistance and aggravate β-cell injuries, thus promoting disease progression." (PMID 24465695, 2014). "Another indicator of chronic inflammation in the vascular bed of the hoof is increased expression of TNFα, which also promotes insulin resistance." (PMID 24894908, 2014). "Reports suggest that the deletion of TNF-alpha leads to increased insulin sensitivity, i.e., decreased insulin resistance." (PMID 24991532, 2014). "The relationship between the immune system and AT was recognized several decades ago when it was shown that neutralizing tumor necrosis factor alpha (TNFα) improved insulin resistance in rodents." (PMID 24701352, 2014). "The monocytes, macrophages, lymphocytes coupled with the cytokines secreted by these cells – in particular, TNF-α and IL-6 – contribute to insulin resistance and atherosclerotic plaques." (PMID 25364704, 2014). "In order to evaluate a potential involvement of TNFα in mediating the effect of monocyte-specific Fas on skeletal muscle insulin resistance, we determined circulating TNFα and LPS levels in the obese human cohort." (PMID 24203314, 2014). "For instance, in both ob/ob and diet-induced obese mice, genetic deletion of TNF-α or its receptors significantly reduced insulin resistance and improved insulin signaling in muscle and adipose tissue." (PMID 24563869, 2014). "The first is TNF-α blockade, which has shown some mixed success in improving insulin resistance in diabetic patients." (PMID 25157251, 2014). "Some other studies suggest that systemic administration of the TNF-α also induces insulin resistance in experimental animal." (PMID 24932457, 2014). "The increased visceral adiposity induces a decrease in adiponectin, which has an anti-inflammatory action, and an increase in inflammatory cytokines, such as tumor necrosis factor-α, interleukin-6, and free fatty acids, which raise insulin resistance." (PMID 25024746, 2014). "Increased plasma PAI-1 and TNF-α levels contribute to the development of thrombosis and insulin resistance, respectively." (PMID 25548896, 2014). "In dairy cows, plasma TNF-α peaks transiently at parturition and decreases thereafter below prepartum values; high TNF-α serum concentrations are associated with insulin resistance and fatty liver 1 to 2 wk after calving." (PMID 24465964, 2014). "TNFα is known to induce insulin resistance in rodents and decrease the expression of insulin receptor, IRS-1, and GLUT4 in 3T3-L1 adipocytes." (PMID 24918199, 2014). "Since we have reported that one pathway by which TNFα can mediate insulin resistance in REC is through phosphorylation of IRS-1Ser307, we measured this phosphorylation site in vivo and found that etanercept reduced IRS-1Ser307 in the β2KO mice." (PMID 25138272, 2014). "Adipocytes secrete substances that contribute to peripheral insulin resistance, including adiponectin, resistin, TNF-alpha and interleukin 6 which interfere with glucose metabolism and exert lipotoxic effects on pancreatic beta cells." (PMID 25374160, 2014). "Several insulin resistance indices, inflammatory cytokines or adipokines, including C-reactive protein, adiponectin, and tumor necrosis factor-α, were all improved in both groups." (PMID 26137510, 2014). "The goal of this study was to demonstrate that TNFα plays a role in insulin resistance in β2KO mice." (PMID 25138272, 2014).
Insulin resistance (continued). "Taking into account these newer studies, a recent meta-analysis concluded that probiotic therapies can reduce liver aminotransferases, total cholesterol, and TNF-α and improve insulin resistance in NAFLD patients." (PMID 25436233, 2014). "TNF-α and IL-6, two well-known pro-inflammatory cytokines, affect insulin action and promote insulin resistance." (PMID 24913911, 2014). "We found that inhibition of TNFα by etanercept treatment to β2KO mice was able to significantly reduce apoptotic markers through decreased activation of TNFα-mediated insulin resistance." (PMID 25138272, 2014). "Inhibition of TNFα by etanercept protects the retina likely through reduced TNFα-mediated insulin resistance, leading to reduced apoptosis." (PMID 25138272, 2014). "PM2.5 exposure led to hyperglycemia and insulin resistance, which was accompanied by increased hypothalamic IL-6, TNFα, and IKKβ mRNA expression and microglial/astrocyte reactivity." (PMID 25358444, 2014). "TNF-α also contributes to insulin resistance, a phenomenon that occurs more often in RA patients than in matched healthy subjects or osteoarthritis patients." (PMID 24620738, 2014). "In this data set, we demonstrate that etanercept is effective at reducing TNFα-mediated insulin resistance." (PMID 25138272, 2014). "It has been reported that insulin resistance and cytokines such as TNF-α, IL-1, IL-2, IL-6, PAF raise serum triglyceride levels while reduce total and HDL-cholesterol levels." (PMID 24772131, 2014). "Conversely, adoptive transfer of CD8+ T cells into CD8-deficient mice increased infiltration of macrophages into VAT as well as expression of the inflammatory cytokines IL-6 and TNF-α, along with development of insulin resistance following high-fat diet." (PMID 25157251, 2014). "The adipocytokines TNFα and IL-6 derived from adipose tissues are strongly suggested to promote insulin resistance and inflammation in the liver." (PMID 24858832, 2014). "It has been shown that TNF-α can induce insulin resistance in humans via serine phosphorylation of the insulin receptor and via inhibition of the Akt substrate 160 phosphorylation." (PMID 24692847, 2014). "T2DM is found to display increased concentrations of C-reactive protein (CRP) and pro-inflammatory cytokines, such as tumor necrosis factor-α (TNF-α) and interleukins 1 and 6 (IL-1, IL-6), which are implicated in instigating metabolic insulin resistance." (PMID 24650557, 2014). "According to our data (Periodic Report 2 - SICA-HF), TNF-α and IL-1β exert NO-independent anti-aggregation effects on isolated human platelets independently on the presence of insulin resistance in the subjects." (PMID 25601838, 2014). "Treatment with TNF-α induces insulin resistance in adipose tissue, whereas deletion of TNF-α or its receptors improves insulin sensitivity in obese animals." (PMID 24733068, 2014). "There is now substantial evidence linking TNF-alpha to insulin resistance in humans, animals and in vitro systems." (PMID 24991532, 2014). "On the other hand, both obese and diabetic patients have associated vascular complications such as atherosclerosis, insulin resistance with hyperinsulinemia and elevated circulating TNF-α levels." (PMID 25077985, 2014). "TNF-α, a pro-inflammatory cytokine, not only promotes insulin resistance, but also mediates cholesterol and TG metabolism." (PMID 24520264, 2014). "To date, a range of adipokines (e.g., IL-6, TNF-α and resistin) have been reported to promote insulin resistance in adipocytes through the STAT3-SOCS3 pathway." (PMID 24516630, 2014). "In particular TNFα and IL-6, originally considered classical inflammatory cytokines, are now considered major links between steatosis, insulin resistance (IR), and related inflammatory disorders." (PMID 24795720, 2014). "Adiponectin-null mice display high levels of TNF-α mRNA and protein and diet-induced insulin resistance, thus explaining the phenomenon of increased TNF-α in obese populations." (PMID 25500563, 2014).
Insulin resistance (continued). "The examination of the biological mechanisms through which sTWEAK improves insulin sensitivity has demonstrated that, in visceral adipocytes, treatment with sTWEAK ameliorates TNFα-induced insulin resistance on glucose uptake." (PMID 24565471, 2014). "Inflammatory cytokines, such as TNF-α, IL-6 and others, have been shown to promote insulin resistance and liver inflammation." (PMID 24489777, 2014). "Accumulating data suggests a direct relationship between TNF-α plasma levels and insulin resistance." (PMID 24563869, 2014). "Macrophages produce various inflammatory proteins such as tumor necrosis factor alpha (TNF-α), monocyte chemoattractant protein-1 (MCP-1), and nitric oxide (NO), which are implicated in insulin resistance and metabolic disorders." (PMID 24142543, 2014). "Some of these stress-related kinases also promote further production of TNF, perpetuating a positive feedback mechanism for sustained TNF activity and chronic insulin resistance." (PMID 24563869, 2014). "Chronic inflammation of visceral adipose tissue (VAT) is a major contributor to insulin resistance mediated by adipose tissue-released adipokines (for example, IL-6, TNFα, MCP-1 and resistin)." (PMID 23837842, 2013). "While the manuscript was under preparation, we came across a report by Konstantinapoulos and co-workers on the identification of methazolamide, using TNFα-induced insulin resistance and following gene expression signature." (PMID 24194903, 2013). "In RA patients who were treated with TNFα inhibiting agents (such as infliximab or etanercept) it was shown that blocking the effect of TNFα reversed the increased incidence of cardiovascular complications and insulin resistance." (PMID 24133492, 2013). "The significance of and possibilities for JNK mediating the role of TNFα in insulin resistance were also proposed in this study." (PMID 24324517, 2013). "Adipokines enlisted in regulation of insulin resistance are adiponectin, leptin, resistin, visfatin, chemerin, TNF-α, IL-1, IL-6, IL-8, IL-10, plasminogen activator inhibitor 1, monocyte chemoattractant protein-1, and retinol binding protein-4." (PMID 24455420, 2013). "To further investigate the mechanism of inflammation-mediated insulin resistance, we searched for microRNAs (miRNAs) that are deregulated in the inflammatory state evoked by TNF-α." (PMID 24349514, 2013). "A clinical trial which consists of 15 women with normal glucose tolerance and developed gestational diabetes mellitus has proved TNF-α as the sole biomarker and predictor for insulin resistance during pregnancy." (PMID 23762871, 2013). "Recent data point to the fact that central resistin induces hepatic insulin resistance by increasing the expression of proinflammatory cytokines, such as IL-6 and TNFα, via an unidentified mechanism mediated by the autonomic nervous system." (PMID 23710116, 2013). "Two important insulin resistance-related inflammatory cytokines namely TNF-α and IL-6 produced by adipose tissue were evaluated by commercially available ELISA kit." (PMID 23590862, 2013). "TNF-alpha induces insulin resistance in endothelial cells and activates NF-kB/NFIL6/CRE through PKC/MAP kinase/JNK/P38 signaling pathways and thereupon provokes an increase in the expression of cyclooxygenase 2 (COX-2)." (PMID 24330637, 2013). "TNF-α induces insulin resistance in BAT and directly inhibits the expression of uncoupling protein-1(UCP1) which is vital for the regulation of body temperature." (PMID 24236066, 2013). "Stevioside proved to be as effective as the antidiabetic agent, rosiglitazone, at enhancing glucose uptake in normal 3T3-L1 adipocytes or in cells induced to insulin resistance via exposure to TNF-α." (PMID 24391675, 2013). "This suggests the inverse relationship of circulating adiponectin levels to IL-6 and TNF-α and insulin resistance in critically ill patients." (PMID 23840093, 2013).
Insulin resistance (continued). "We have previously reported an important role of TNF-α in the pathogenesis of vascular disease in insulin resistance." (PMID 23717483, 2013). "Other cytokines, such as tumor necrosis factor (TNF)-α and interleukine (IL)-6, have also been related to insulin resistance." (PMID 23482058, 2013). "It is known that both dexamethasone and TNF-α induce insulin resistance by promoting oxidative stress." (PMID 24194903, 2013). "Chronic low-grade inflammation and pro-inflammatory cytokines, such as TNF-α and IL-6 as well as others, contribute to the development of glucose intolerance and insulin resistance-related metabolic syndrome and T2D." (PMID 23326455, 2013). "Vitamin D attenuates the expression of proinflammatory cytokines involved in insulin resistance such as interleukins, IL-1, IL-6, TNF-a, also down regulates NF-Kb (Nuclear factor) activity." (PMID 23443033, 2013). "Examination of the biological mechanisms through which sTWEAK improves insulin sensitivity has demonstrated that, in visceral adipocytes, treatment with sTWEAK ameliorates TNFα-induced insulin resistance on glucose uptake." (PMID 24416031, 2013). "PPAR-γ agonists are noted to have anti-TNFα effects in adipocytes and thus improve insulin resistance." (PMID 24025484, 2013). "A chronic inflammatory state leads to the production of truncal fat adipokines (e.g., TNF-α, IL-6, and IL-8) which increase insulin resistance and endothelial dysfunction." (PMID 23843781, 2013). "For example, in diabetic rats, administration of tumor necrosis factor α (TNF-α) caused hyperglycemia, and, in obese rats, neutralization of TNF-α improved insulin resistance." (PMID 24020899, 2013). "Recent data has focused on the roles of adipose tissue-derived mediators, such as adiponectin, leptin, resistin, tumor necrosis factor-alpha (TNF-α), visfatin, apelin, and chemerin in the pathogenesis of insulin resistance and inflammation." (PMID 23691290, 2013). "It must be noted that leptin, IL6 and TNF are pro-inflammatory cytokines with a recognised role in the development and progression of insulin resistance, T2DM and cardiovascular disease." (PMID 23298335, 2013). "In TNF-α induced insulin resistance, glucose uptake was maximally increased by rosiglitazone or insulin at 90 μM either in presence or absence of insulin." (PMID 24391675, 2013). "Both JNK and TNFα play major roles in the progression of insulin resistance and are discussed later in this review." (PMID 24324517, 2013). "A recent study has confirmed that anti-TNF-α therapy improves insulin resistance, beta-cell function, and reverted defects in the insulin signaling cascade in active RA patients with high insulin resistance." (PMID 23431244, 2013). "We used ELISA to examine pro-inflammatory cytokines IL-1, IL-6 and TNFα in the plasma, which are primarily involved in insulin resistance and T2D." (PMID 23837842, 2013). "TNF-α treatment in cell lines and rodents induces insulin resistance, and neutralization of TNF-α in obese fa/fa rats enhances insulin sensitivity." (PMID 23781214, 2013). "Our findings demonstrate that elevated serum A-FABP concentrations in patients with critical illness were positively correlated with APACHE II scores, inflammatory cytokine TNF-alpha and insulin resistance." (PMID 23375099, 2013). "We will rather focus on the prototypical adipokines (TNF-α, IL-6, leptin, adiponectin, and resistin) highlighting their roles in the development of insulin resistance as well as in immunity and inflammation." (PMID 24455420, 2013). "FL83B mouse hepatocytes were treated with tumor necrosis factor-α (TNF-α) to induce insulin resistance to investigate the effect of a wax apple aqueous extract (WAE) in insulin-resistant mouse hepatocytes." (PMID 23389304, 2013).
Insulin resistance (continued). "Tumor necrosis factor-α (TNF-α), which plays a role in insulin resistance, has been reported to inhibit the follicle stimulating hormone (FSH)-induced follicular development and steroidogenesis in an in vitro mouse preantral follicle culture system." (PMID 24079935, 2013). "FFAs as well as tumor necrosis factor alpha (TNFα) are factors released from adipose tissue that contribute to insulin resistance." (PMID 23690773, 2013). "It has been shown that TNF-α can affect insulin resistance by regulating adipocyte gene expression, and that insulin resistance is an important pathophysiological mechanism of T2DM." (PMID 23527193, 2013). "TNF-alpha is an inflammatory cytokine, strongly correlated with insulin resistance and chronic inflammation." (PMID 24259948, 2013). "Increased peripheral insulin resistance has been coupled with elevated expression of bioactive inflammatory mediators including adipokines (IL-6 and TNF-alpha) which lead to insulin resistance." (PMID 23671867, 2013). "Taking together all these considerations, anti-TNF-α therapy exerts beneficial metabolic effects by the reduction of insulin resistance and improvement of insulin sensitivity." (PMID 23431244, 2013). "The deteriorative ability of TNF-α on insulin resistance in vivo is evident from the fact that TNF-α is highly expressed in adipose tissue, muscle and serum of obese subjects and obese animals." (PMID 24349514, 2013). "States indicative of Type II diabetes were indicated by insulin resistance induced by TNFα, through the inhibition of tyrosine (tyr) phosphorylation of IRS1." (PMID 24324517, 2013). "In the context of insulin action, M2 macrophages sustain insulin sensitivity by secreting IL-4 and IL-10, while M1 macrophages induce insulin resistance through the secretion of proinflammatory cytokines, such as TNFα." (PMID 23964268, 2013). "TNF-α can indirectly contribute to adipocyte insulin resistance by promoting lipolysis and/or by inhibiting differentiation." (PMID 23099484, 2013). "During high fat diet consumption, ATM production of TNFα and IL-6 is closely related to the onset of insulin resistance and glucose intolerance." (PMID 23469154, 2013). "TNF-α induces adipocytes apoptosis and promotes insulin resistance by the inhibition of the insulin receptor substrate 1 signaling pathway." (PMID 23690772, 2013). "Altogether, the present study concludes that the upregulation of miR-494 expression by TNF-α-mediated inflammation exacerbates insulin resistance." (PMID 24349514, 2013). "The chronic inflammatory processes are characterized by the production of proinflammatory cytokines, such as tumor necrosis factor α (TNFα) and interferon α (IFNα), resulting in the impaired clearance of TG-rich lipoproteins and insulin resistance." (PMID 24319689, 2013). "Since glucose uptake went down furthest at 1.0 ng/mL, this concentration was selected as the optimum TNF-α concentration to induce insulin resistance in cells." (PMID 24391675, 2013). "To define mechanisms for PCB-induced impairment of glucose and insulin tolerance, we quantified expression levels of TNF-α in organs contributing to insulin resistance." (PMID 23099484, 2013). "TNF-α also induces serine phosphorylation of IRS1 to modulate the downstream effectors of the insulin receptor resulting in insulin resistance." (PMID 23781214, 2013). "This provides a platform for the implementation and use of TNFα in insulin-resistance studies, as a factor to induce insulin resistance in the cells of interest." (PMID 24324517, 2013). "Further, TNF-α expression is increased in adipose tissue in obese rodents and humans, and reducing TNF-α signaling either by knocking TNF-α out or by infusing blocking antibodies can reduce insulin resistance in obese rodents." (PMID 23762871, 2013). "In 3T3-L1 adipocytes, insulin resistance induced by tumor necrosis factor (TNF) is accompanied by an increased expression of GM3 synthase activity and GM3 ganglioside." (PMID 24709879, 2013).